CCL5 (C-C motif chemokine ligand 5)
Diseases named in the same sentence as CCL5 in open-access papers (continued):
Sharing a sentence is not in itself a finding about the gene and the disease.
tumor (continued). "In addition, IFNγ-driven increased expression of chemokines in tumors of Dox-treated mice, such as CCL2, CCL3, CCL5, and CXCL16 has been associated with enhanced recruitment of CD8+ T cells to tumors and reduced tumor progression." (PMID 37478172, 2023). "Several studies have found that tumor‐derived CCL5 can bind to CCR5 expressed on macrophages." (PMID 36794651, 2023). "An experimental model of low-grade optic gliomas with mutation of neurofibromin 1 (NF1) showed increased expression of chemokine C-C ligand 5 (CCL5), along with other chemokines responsible for tumor growth, and increased attraction of T cells and microglia into tumor tissue." (PMID 38275375, 2023). "Increased expression of CCL5 has been found in the tumor tissues of CRC patients who drank alcohol." (PMID 37141250, 2023). "Similarly, CCL2 and CCL5 released by CSCs contribute to both macrophage infiltration and skew them towards the tumor-supporting M2 subtype." (PMID 38035101, 2023). "Remarkably, we found that the chemokine CCL5 secreted by PD1 + T cells could combine with SDC1/4 on the surface of all PD-L1 + tumor clusters (Tumor1-6)." (PMID 36944944, 2023). "Using multiplex immunoassays, we examined type I IFN (IFN-α, IFN-β), type II IFN (IFN-γ), proinflammatory cytokine (GM-CSF, IL-6, IL-12p70), and proinflammatory chemokine (CXCL10 [IP-10], CCL2 [MCP-1], CCL3 [MIP-1α], CCL5 [RANTES]) signaling in the tumor microenvironment (TME)." (PMID 36810257, 2023). "For instance, it is revealed that osteopontin as a tumor-derived inflammatory cytokine promotes CA-MSCs to the secret high level of CCL5, which binds to its receptor (CCR5) on cancer cells to enhance cancer cells’ metastatic potential and MSCs’ ability to migrate to metastasis site." (PMID 38022534, 2023). "In addition to acting directly on CRC cells as a tumor-promoting factor, CCL5 appears to be a regulator of inflammatory cell infiltration into tumor tissue." (PMID 37141250, 2023). "This is in accordance with previous reports demonstrating that the main producers of tumor-associated CCL5 are not the tumor cells themselves, but the local mesenchymal stromal cell population." (PMID 37444610, 2023). "Interestingly, CD73 depletion-induced tumor growth inhibition was largely abolished by injection of CCL5." (PMID 37291128, 2023). "However, the same cells increased the recruitment of neutrophils through interleukin 8 (IL-8) secretion and attracted cytotoxic CCR5+CCR6+CD8+T cells into tumor tissue through CCL5 and CCL20 production." (PMID 37185750, 2023). "Thus, serum CCL5 levels were correlated with both tumor‐promoting markers at baseline and anti‐tumor markers after the introduction of Atez/Bev therapy." (PMID 38133557, 2023). "Indeed, inducing CCL5 expression is able to rescue the anti-angiogenic effects caused by RKIP expression, suggesting that the regulatory role of RKIP in tumor angiogenesis involves indirect pathways." (PMID 36765912, 2023). "Notch induced CCL5 secretion and CCR5 signaling in tumor-associated macrophages." (PMID 37759462, 2023). "Additionally, CMS4 tumors express chemokines such as CCL-2, CCL-5 and CXCL-12 that attract myeloid cells, leading to the infiltration of cancer-associated fibroblasts (CAFs), MDSCs and tumor-associated macrophages (TAMs)." (PMID 37511431, 2023). "CCL5 binds to the receptor CCR5 and plays a role similar to that of oncogenes that is, it promotes tumor growth, induces extracellular matrix remodeling, recruits immune cells and polarizes tumor-associated macrophages (TAMs)." (PMID 37141250, 2023). "Furthermore, the positive correlation between CD73 and CCL5 expression was confirmed by immunoblotting in 14 paired clinical tissue samples and IHC staining in 26 tumor samples." (PMID 37291128, 2023). "Additionally, CCL5 knockdown in tumor cells also prevented DU102-induced tumoral infiltration of T cells in vivo." (PMID 39872623, 2023).
tumor (continued). "Although chemotherapy may induce a pro-tumorigenic immune response, chemotherapeutics also activate the STING (STimulator of INterferon Genes) pathway, which induces CCL5 and may thereby induce PD-L1 expression and a tumor immunosuppressive environment." (PMID 37759462, 2023). "Indeed, we have demonstrated previously that nuclear FAK induces the expression of proinflammatory cytokines and chemokines, including IL-33 and CCL5, which inhibit antitumour immunity and drive tumour growth in vivo." (PMID 36959177, 2023). "Furthermore, macrophage annexin 1 (ANXA1), induced by tumor cell‐derived CCL5, is important in regulating polarization and activation of M2‐type macrophages." (PMID 36794651, 2023). "However, other studies have reported that, by upregulating CCL5 expression, oncolytic viruses can recruit NK cells to induce tumor regression." (PMID 37854606, 2023). "In addition, we identified that interleukin-8 and interleukin-1β cytokines are involved in macrophage polarization, and the chemokine CCL5/RANTES in the macrophages recruitment at the tumor site." (PMID 37488586, 2023). "CCL5 could promote an anti-tumor response by recruiting anti-tumor immune cells to the TME, which enhance the immunotherapy response." (PMID 37509334, 2023). "In addition, inhibiting the exosomes miRNA-155 of tumor cells can reduce the levels of CCL2 and CCL5 in CAAs co-culture thereby inhibiting tumor growth." (PMID 37666813, 2023). "The seemingly contradictory findings suggest that the detailed mechanism by which CCL5 acquires its tumor suppressor/promoter function in CRC development is largely unknown." (PMID 36387070, 2022). "Anti-CCL5 antibodies blocked the effect of CAFs on tumor growth and migration." (PMID 36439168, 2022). "CRC tumor buds overexpress and secrete CCL5. artificially added CCL5 (in vitro)." (PMID 36387070, 2022). "CCL5 released by tumor-activated platelets mediates migration and chemotaxis of T lymphocytes and monocytes, and anti-chemokine receptor-5 therapy causes tumor-associated macrophages to switch from pro-tumor to anti-tumor roles in patients with liver metastases." (PMID 35936717, 2022). "Tumour-infiltrating T cells stimulate the expression of CCL5, promoting CRC metastases." (PMID 35692800, 2022). "In addition, there was a high level of infiltration of M2 macrophages in the stromal and tumor tissues with high expression of CCL5." (PMID 35982911, 2022). "Therefore, knockdown of CCL5 facilitates CD8+ T-cell infiltrate into the central tumor area and delays tumor growth and metastasis." (PMID 35935996, 2022). "However, tumor patients with high CCL5 protein expression in some CRC patients indicates a better prognosis." (PMID 36387070, 2022). "In addition to influencing innate cells, CCL5 promotes tumor metastasis via the induction of CD4+ T cell polarization and enhances the infiltration and function of Tregs." (PMID 35327361, 2022). "The conclusion that CCL5 mainly comes from tumor cells has also been reported in previous studies." (PMID 36033472, 2022). "Based on the finding that CCR5 antibodies retard tumor progression and inhibit angiogenesis, we speculate that CCL5/CCR5 may be a potential target in cancer therapy." (PMID 35702353, 2022). "However, limited evidence suggests inhibition of the autophagy protein Beclin1 in melanoma cells stimulates the infiltration of effector NK cells into the tumor bed through CCL5-dependent mechanism leading to the suppression of the tumor." (PMID 35912261, 2022). "The growing number of studies accompanying the interaction between CCL5 and immune cells suggests that the CCL5/immune cell axis may be a promising target for cancer immunotherapy to achieve tumor regression, including in CRC." (PMID 36387070, 2022). "We speculate that this is also the reason for the accumulation of a large amount of CCL5 in tumor tissues." (PMID 36033472, 2022).
tumor (continued). "M1-secreted CCL2, CCL5 or IFN-β may increase neutrophil infiltration to the tumor location and contribute to pro-inflammatory neutrophil-targeted tumor regression." (PMID 36325334, 2022). "Previous studies have proved that CCL5 mainly expressed in T-lymphocyte subsets of blood cells; our reverse-transcription polymerase chain reaction (RT-PCR) results also showed that T-lymphocytes was the main source of CCL5 in splenocytes of tumor-bearing mice." (PMID 35707772, 2022). "Likewise, CCL5 can attract Tregs to the tumor-site, whereas high levels of IL-10 and TGF-β in the TME stimulate the differentiation of naïve T cells into Tregs." (PMID 35740542, 2022). "Tumor samples were divided into high and low groups according to median CCL5 expression levels." (PMID 35252266, 2022). "CCL5 also stimulates pro-angiogenic signals by regulating endothelial cell migration, neovessel formation, and vascular endothelial growth factor secretion in tumor cells." (PMID 35982911, 2022). "Second, analyses performed on tumor lysates revealed that chemokines involved in myeloid cell migration (CCL5, CCL2, CCL4), together with inflammatory (IL-1β and TNFα) and pro-angiogenic factors (VEGF-A, VEGFR2, PDGF, Endoglin) were increased in tumors of mice fed a HFHCD." (PMID 36104342, 2022). "Activated TAMCs could express CCL5 and IL-33 to further recruit MCs into tumor sites and activate themselves in an autocrine manner." (PMID 36168626, 2022). "CCL5 is a target gene of NF-κB activity and is expressed by T lymphocytes, macrophages, platelets, synovial fibroblasts, tubular epithelium, and certain types of tumor cells." (PMID 35208526, 2022). "Both tumor mesenchymal stem cells and tumor-activated platelets may release the chemokine ligand 5 (CCL5)." (PMID 35936717, 2022). "The authors speculate that CCL5 acts as a double-edged sword—initially fueling tumor development, but also recruiting antitumor cell populations to the zone over time." (PMID 36430633, 2022). "FBN1 is highly expressed in this cluster, indicating activity in an extracellular matrix organization and EMT process; CAF in metastatic microenvironment highly expresses CCL5 which promotes the migration of tumor cells; while high expression of tumor-suppressive genes such asTFF1 was also detected." (PMID 36148946, 2022). "Data suggest that while the source of the CCL5 is the tumor, the cells expressing CCR5 are stromal." (PMID 36430633, 2022). "Interestingly, an examination of 17 paired tumor, normal, and metastatic lymph node (mlymph node) tissues showed significantly higher expression of CCL5 in mlymph node tissues compared to the tumor and normal samples (P<0.01)." (PMID 35982911, 2022). "Together, these results revealed that CCL5 was highly expressed in CRC tumor buds and could recruit fibroblasts from the TME." (PMID 35241150, 2022). "Therefore, to investigate the role of CCL5 in cryo–thermal-induced anti-tumor memory immunity, we explored the therapeutic effect of cryo–thermal therapy on CCL5−/− mice with the 4T1 model." (PMID 35327361, 2022). "However, studies have shown that CCL5 promotes antitumour immunity by recruiting antitumour T cells and DCs to the tumour microenvironment." (PMID 35365161, 2022). "Given the sheer wealth of detailed research showing CCL5 as a pro-tumor chemokine, it could be an ideal candidate marker for a highly impactful new mRNA-based drug." (PMID 36430633, 2022). "However, anti-PD-L1 treatment resulted in upregulation or downregulation of numerous genes in CD45+ tumor-infiltrating immune cells in TCh3 tumors, including Cd3d, Cd3e, Cd3g, Cd8a, Cd8b1, Nkg7, Ccl5, Ets1, Icos, Cxcr6, Pdcd1, Lag3, Prf1, and Gzmb (right)." (PMID 35366939, 2022). "In addition, relevant cytokines for acquiring a tumor malignancy phenotype, such as CCL5/RANTES, have also been shown to increase cell motility and invasiveness in high-glucose culture conditions." (PMID 35268073, 2022).
tumor (continued). "Next, we tried to figure out if depletion of CCL5 protein could induce tumor patients-derived MDSCs into CD24+MDSC-DCs with similar antitumor function as murine CD24+MDSC-DCs." (PMID 35707772, 2022). "Likewise, CCL5, which is mainly secreted by T cells, has been linked to a pro-tumorigenic effect as its interaction with the cognate receptor CCR5 triggers tumor cell proliferation and progression into a more aggressive phenotype." (PMID 36297669, 2022). "Those lymphocytes secrete CCL5, which leads to tumor growth and invasion." (PMID 35935996, 2022). "Nevertheless, the biological effect of tumor-derived CCL5 on fibroblasts remains elusive." (PMID 35241150, 2022). "Consequently, the findings indicate that the accuracy of the pathological diagnosis of tumor budding in CRC can be increased by examining CCL5 expression." (PMID 35241150, 2022). "Moreover, tumor-derived CCL5 enhances TGF-β secretion in T regulatory cells via the CCL5/CCR5 axis, thereby blocking the killing function of CD8+ T cells." (PMID 35241150, 2022). "Additionally, efferocytosis of apoptotic cancer cells by macrophage populations leads to production of an array of factors, including CXCL5, IL-6, IL-8, CCL4, and CCL5, which promote tumor growth and survival." (PMID 35159026, 2022). "Although there is a high tumor heterogeneity for TAMs within ccRCC, we found that increased abundance of tumor-infiltrating CCL5+ TAMs represented worse OS and PFS compared to tumors with lower CCL5+ TAMs-infiltration in ccRCC patients (OS, P<0.0001, HR=1.923; PFS, P=0.0003, HR=1.807)." (PMID 35982911, 2022). "In this study, CCL5 was found to be a marker for tumor budding." (PMID 35241150, 2022). "In a mouse tumor model, it was shown that radiation therapy triggers the secretion of CXCL1, CXCL2, and CCL5, which leads to neutrophil recruitment to tumor sites; in turn, neutrophils generate ROS and suppress PI3K/AKT/SNAI1 signaling, inhibiting epithelial–mesenchymal transition." (PMID 36555469, 2022). "In addition, studies have confirmed that CCL5 secreted by tumor cells recruits Treg cells through CCR5 to stimulate TGF-β to block the tumor killing function of CD8+ T cells, promoting tumor progression." (PMID 36033472, 2022). "A recent study showed that the chemokine Rantes (CCL5) is a key chemokine determining whether the tumor will be attacked by effector T cells." (PMID 35892755, 2022). "Interestingly, CCR5 ligands: CCL3, CCL4 and CCL5 were detected in the majority of supernatants harvested from dissociated tumour biopsy and CUSA, but little was detected in GNS cell supernatants." (PMID 35464424, 2022). "CCL5 is a key chemokine for CD8+ T cells to enter tumor cells." (PMID 35401204, 2022). "CCL5/CCR5 signaling mediates signal transduction cascades related to tumor progression, including PI3K/Akt, JAK/STAT3, MAPK/ERK, and NF-kB, involving in tumor growth, metastasis, cancer stem cell expansion, DNA damage repair, and angiogenesis and metabolic reprograming." (PMID 35784750, 2022). "By binding to and activating CCR5, CCL5 generated by melanoma tumor cells may trigger the death of tumor-infiltrating T lymphocytes." (PMID 35573839, 2022). "Importantly, downregulation of miR-214 increases the production of CCL5, leading to accelerated tumor growth." (PMID 36439168, 2022). "Moreover, CCL5 also functions as a pro-tumor effector by promoting cancer cell proliferation, survival, motility, epithelial–mesenchymal transition (EMT) and stemness maintenance." (PMID 35359417, 2022). "Many studies considered that CCL5 promotes tumor migration, invasion, and even immune escape." (PMID 35935996, 2022). "The researches showed when CCL5 attracted T cells to the tumor and activated cancer antigens." (PMID 35145917, 2022). "Its increase by neutrophils could indicate considerable signaling to monocytes in the tumor microenvironment that, once attracted, could be polarized to the M2-like phenotype with the aid of CCL5, thus increasing the inflammatory response." (PMID 35741003, 2022).
tumor (continued). "On the other hand, CCL5 and its receptor complex may stimulate tumor cells to produce more CCL5, thus forming a positive feedback loop." (PMID 36033472, 2022). "TAMs secrete CCL5 to activate the STAT3β-catenin pathway and favor the metastasis of tumor cells." (PMID 36246629, 2022). "Evaluating the influence of chemokines in OC, we could conclude that the overexpression of VEGF and CCL2 and the reduction in CCL5 in MA may provide a facilitating pathway for tumor dissemination in the peritoneal cavity." (PMID 36142615, 2022). "In the future, we will clarify that whether circCYP24A1/ PKM2/ NF-κB could affect tumor microenvironment by promoting the paracrine and distal secretion of CCL5." (PMID 36514094, 2022). "In support of this, in mouse lung cancer, also IL-33 was related to good prognosis since it could elevate the frequency of tumour infiltrating ILC2s via CCL5, CXCL10, and CXCL12." (PMID 35406451, 2022). "Selectins also engage in endothelial activation caused by complicated interactions between tumor cells, platelets, and leukocytes, and then upregulate the expression of C-C chemokine ligand 5 (CCL5), which promotes the survival of tumor cells and leads to local lung metastasis." (PMID 36497322, 2022). "In vitro experiments demonstrated that CCL5 derived from tumor buds could recruit fibroblasts by acting on the CCR5 receptors on fibroblasts." (PMID 35241150, 2022). "The high correlation between their tumor budding and high CCL5 expression suggests that CCL5 may be a potential diagnostic marker and therapeutic target for CRC tumor budding." (PMID 36387070, 2022). "Similarly, we included 533 tumor and 72 adjacent normal kidney samples with available transcriptome profiles from the TCGA database and observed that CCL5 mRNA expression was significantly higher in ccRCC compared with normal kidney samples (P<0.0001)." (PMID 35982911, 2022). "CCL5 may also promote the survival, proliferation, and invasion of tumor cells through different mechanisms." (PMID 36387070, 2022). "Compared to virus-specific Th1 cells, this tumor-specific CD4+ T cell state differentially expressed genes associated with Th2 cells, including Igfbp7, Ccl1, Ccr8, and Il13, and downregulated Th1-associated genes, including Ccl5 and Ly6c2." (PMID 35829695, 2022). "To evaluate the dynamic reversible process of TME regulation by TILs and chemokines, we enrolled 20 paired ccRCC and normal tissues from the FUSCC cohort and performed IHC staining analysis to assess the protein expression of CCL5 in the tumor, stromal, and normal samples." (PMID 35982911, 2022). "Tumor bud-derived CCL5 could also positively regulate solute carrier family 25 member 24 (SLC25A24) expression in fibroblasts, potentially activating pAkt-pmTOR signaling." (PMID 35241150, 2022). "Further studies are necessary to dissect the exact contribution of various factors, such as the role of CCL5 in the tumor microenvironment or immune system, and most studies have shown that modulation of CCL5 signaling appears to be an effective approach to provide therapeutic options against CRC." (PMID 36387070, 2022). "Since multiple secreted factors identified above, including AREG, PAI-1, CCL2, CCL5, IL6, IL8, and CSF2, are also known to be regulated by yes associated protein (YAP), we investigated whether V2R regulates YAP in ccRCC tumor cells." (PMID 35886951, 2022). "Furthermore, we measured the circulatory and tumor associated levels of CCR5 and its ligands (CCL3, CCL4, CCL5) in serum (ELISA), primary tumors (qRT-PCR; IHC) and matched liver metastases (IHC) from CRC patients to assess potential morbidity-related changes." (PMID 32902795, 2021). "Chemokines have important roles in the interactions between carcinoma cells and stromal cells in the tumor microenvironment, and CCL5, a member of chemokine family, is expressed in many stromal cells, such as macrophages, fibroblasts, lymphocytes and adipocytes, in various types of cancers." (PMID 33671956, 2021).